CD34 (CD34 molecule)
Diseases named in the same sentence as CD34 in open-access papers (continued):
Sharing a sentence is not in itself a finding about the gene and the disease.
lymphoma (continued). "In particular, a bone marrow analysis is necessary to determine whether the CD34 expression identified in this study is an aberrant immunophenotype, precursor lymphoma, or acute lymphoblastic leukemia, and peripheral blood tests are insufficient." (PMID 37908841, 2023). "Interestingly, we observed CD34 in five glioses (two AV malformations, a lymphoma, a chronic hematoma, and a metastasis of carcinoma)." (PMID 37568909, 2023). "In case of precursor lymphoma, antigens expressed in lymphocytes at a relatively early stage of differentiation, including CD34, may also be identified." (PMID 37908841, 2023). "We suggest that GDP/R-GDP plus G-CSF can be used as an effective chemotherapy regimen for mobilizing CD34+ stem cells from peripheral blood in relapsed and refractory lymphoma patients due to low toxicity, effective tumor reduction, and successful stem cell mobilization." (PMID 33237657, 2021). "CTLA-4 significantly increased the proportion of CD44+ CD34+ cells in lymphoma cells, and TGF-β neutralization could significantly block this effect of CTLA-4." (PMID 34553071, 2021). "All 433 lymphoma patients who underwent ASCT for lymphoma at Karolinska Huddinge 1994–2016 were investigated, including CD34+ cell amounts, medications, infectious and other complications, intensive care, longitudinal laboratory values, and secondary myeloid neoplasia." (PMID 30923643, 2019). "Indeed, immunohistochemistry showed that Ldha wildtype or mutant lymphomas from λ-Myc mice exhibited a remarkable sparse expression of angiogenic markers CD34 and SMA." (PMID 22438825, 2012). "Finally, considering the more frequent use of novel agents and antibodies in MM and lymphoma, now and in the future, it is necessary to improve the efficiency of stem cell mobilization, reducing days of leukapheresis and targeting CD34+ collected with cost-effective agents." (PMID 38607025, 2024). "However, in the case of CD34+ B-cell lymphoma, considering various clinical and immunophenotypic characteristics, and tumor course, the possibility of acute leukemia or precursor lymphoma was estimated to be low." (PMID 37908841, 2023). "It is our standard practice at the Mayo Clinic, Rochester, MN that any lymphoma patient undergoing ASCT will not only have enough CD34 stem cells (4.0 × 106 cells/kg) collected to facilitate hematologic engraftment but also A-ALC ≥ 0.5 × 109 cells/kg to impact ALC-15 and survival post-ASCT." (PMID 35883639, 2022). "The expression of LCA and CD34 may be misdiagnosed as lymphoma and acute leukemia, respectively." (PMID 36290813, 2022). "Clinically, CD34 is not considered part of the diagnostic antibody panel for lymphoma." (PMID 32010428, 2020). "On the other hand, MCL1 expression was significantly higher in healthy CD34 + cells compared to healthy MSC and lymphoma cell lines." (PMID 39531065, 2025). "Both NT5E and CD34 genes presented a lower risk of death or relapse, also adjusted by age, sex and EBV infection, suggesting that, at least in this preliminary series, they may have significant consequences for lymphoma development, progression and response to treatment." (PMID 40461625, 2025). "Higher peak circulating CD34+ values were achieved after chemotherapy-based mobilization comparing to steady state mobilization in both PCN and lymphoma patients, p< 0.001 and p = 0.004, respectively." (PMID 38235620, 2024). "Among the T cells, one dog was identified as CD34+ and CD4-/CD8-, suggesting the possibility of precursor lymphoma." (PMID 37908841, 2023). "To validate the bioinformatics results, we examined the expression of HBO1 protein in CD34+ cells from healthy human peripheral blood and various ALL, AML, and lymphoma cell lines." (PMID 37542030, 2023). "Further research in a larger cohort of patients with a wider range of malignancies, including lymphoma, is needed to verify this and to clarify the optimal timing of PBSC harvest and of CD34+ cell monitoring in peripheral blood." (PMID 35396889, 2022).
lymphoma (continued). "All lymphoma patients were tested for CD3, CD4, CD8, CD11a, CD5, CD21, CD34, CD79acy and MHCII expression." (PMID 34268346, 2021). "An extremely important step in the treatment of multiple myeloma and lymphomas is the adequate mobilization of HSC, as this is essential for obtaining a sufficient number of CD34+ cells needed for auto-HSCT." (PMID 34356523, 2021). "Differential diagnosis was performed via immunohistochemistry (IHC), showing a loss of BRG1 and claudin-4, SALL4 expression, CD34, SMARCAB1, and negative lymphoma markers." (PMID 38542211, 2024). "The typical phenotype of BL (CD19 + /CD10 + /BCL2-/Ki67 > 95%/TdT-/CD34-/sIg +) with appropriate cytomorphology, demonstration of MYC-R alone, and simple karyotype differentiates MYC/BCL2 “double hit” lymphomas and lymphoblastic leukemia/lymphoma." (PMID 37530792, 2024). "BM biopsy showed hypercellularity and the CD3+ lymphoma cells were negative for CD45, CD34, CD117, TdT, CD79a, and Epstein‐Barr virus‐encoded RNA (EBER) staining, with the pattern of sinusoidal infiltration." (PMID 37206287, 2023). "However, other lymphoma markers like CD3, cyclin D1, cytokeratin, epithelial membrane antigen (EMA), vimentin, B-cell lymphoma 2 (BCL2), CD117, CD34, desmin, and smooth muscle actin (SMA) were positive only in 1 case each." (PMID 36511607, 2023). "Next, we silenced LTβR expression in FACS-purified BM CD34+ HSPCs from untreated staging negative lymphoma patients (control samples) using small interfering RNA (siRNA)." (PMID 33594067, 2021). "In contrast to our observation, the only report analyzing G-MDSCs in lymphomas found, in a cohort of 60 HL patients, a prognostic significance for immature CD34+ MDSCs but not for G-MDSC." (PMID 27050283, 2016). "Immunohistochemical analysis showed strong diffuse positivity for CD99, alongside vimentin, BCL2, Cyclin D1, and C-Kit expression, while markers such as CK7, CK20, S100, and CD34 were negative, effectively ruling out differential diagnoses such as rhabdomyosarcoma, lymphoma, and other SRCTs." (PMID 41466962, 2025). "Rarely, T-lymphoblastic leukemia/lymphoma with an entirely mature immunophenotype, lacking expression of TdT, CD34, CD1a, and CD99, has been reported in children, and has been associated with poor prognosis, as have cases of T-lymphoblastic leukemia/lymphoma that are TdT negative." (PMID 40227608, 2025). "In addition, we carried out a sub-analysis on lymphoma and myeloma patients separately by PSM to generate different pair wise groups with balanced distribution of specific baseline features (age, gender, and number of infused CD34 +)." (PMID 38189833, 2024). "Although aberrant expression of CD34 has been observed in lymphoma without bone marrow involvement, its biological significance remains unclear." (PMID 37908841, 2023). "In other lymphoid hematologic malignancies such as lymphoma, MM, ALL, and CLL than AML, there could be some differences according to the percentages of both malignant cells and CD34+CD38− compartments within bone marrows because of niche competition between two cell populations." (PMID 32252668, 2020). "Ectopic expression of JAM-A stimulated lymphoma cell colony formation (P = 0.0354 and P = 0.0398) and induced higher expression of cancer stem-cell marker CD133 and CD34 than those of control vector (Vector) (P = 0.0003 and P = 0.0061 for CD133, P = 0.0197 and P = 0.0250 for CD34)." (PMID 28785100, 2017). "B-lymphoblastic leukemia/lymphoma with TCF3::PBX1 fusion is typically strongly positive for CD9, dim-to-negative for CD34, and dim-to-negative for CD20." (PMID 40227608, 2025). "Accordingly, exposure of 40 nM VEN led to significantly diminished cell numbers in both lymphoma cell lines, while healthy MSC and CD34 + HSPC were not as drastically affected." (PMID 39531065, 2025). "Immunohistochemical analysis showed that the lymphoma expressed CD10, CD20, and BCL6 but was negative for CD34, BCL2, and TdT." (PMID 36171838, 2022).
lymphoma (continued). "In contrast, dilated sinusoids, which can also be present in some splenic lymphomas, are lined by littoral cells (CD8-positive/CD34-negative) and vascular endothelial cells (CD8-negative/CD34-positive)." (PMID 34940070, 2021). "BM flow cytometry gating on the lymphoma cells confirmed the positive expression of CD2, CD3, CD7, CD8, CD56, T‐cell receptor (TCR) alpha‐beta chains, perforin, granzyme B, and negative for CD34, CD4, CD5, and TCR gamma‐delta chains, consistent with natural killer (NK)/T lymphoma involvement." (PMID 37206287, 2023). "For example, CLL/SLL cells are positive for CD5, CD23, CD200, dim for CD20 and CD81, and negative for FMC-7; in MCL, lymphoma cells are positive for CD5, and negative for CD23; and in FL, lymphoma cells are positive for CD10 and CD20, and negative for CD34 and TdT." (PMID 34879826, 2021). "Although markers such as CD34, cytoplasmic CD3 or deoxynucleotidyl transferase may help define the origin and identity of the immature T-cell lymphomas in our study, we did not perform this immuno-profiling on the lymphoma samples." (PMID 37145994, 2023).
multiple myeloma (71 papers, 2007 to 2026). "Efficient mobilization of CD34+ hematopoietic stem cells plays a vital role in successful autologous stem cell transplantation (ASCT) in patients with multiple myeloma (MM), especially in cases with high-risk cytogenetic recommended for tandem ASCT." (PMID 35155259, 2022). "Our results suggest that high levels of mobilised peripheral CD34+ cells are associated with favourable outcome in myeloma patients undergoing autologous transplantation." (PMID 21878938, 2011). "In conclusion, this study identified high levels of circulating CD34+ cells at the day of stem cell collection to be associated with favourable outcome in myeloma patients undergoing autologous transplantation." (PMID 21878938, 2011). "This systematic review examines the available clinical data on CD34+ cell mobilization, collection, and engraftment in multiple myeloma patients treated with the anti-CD38 monoclonal antibodies daratumumab and isatuximab in clinical trials and in real life." (PMID 39065794, 2024). "Two myeloma patients, who received concurrent lenalidomide (D-Rd and D-VRd), required plerixafor for mobilisation with stem cell yields of 2.5 and 5.19 x106 CD34+ cells/kg, respectively." (PMID 39417013, 2024). "The CD34+ stem cell yields were adequate in the majority of myeloma patients with a median 10.7 × 106 cells/kg body weight." (PMID 39194701, 2024). "In myeloma clinical setting, CD34 + stem cells with minimal contamination from clonotypic cells are used in hematopoietic stem cell transplantation as it is believed that myeloma cells lack CD34." (PMID 37120508, 2023). "As per the International Myeloma Working Group recommendations, a CD34+ stem cell count of ~8×106/kg should be administered with a minimum target of 4×106 cells/kg." (PMID 37155458, 2023). "Only two patients (the first one with r/r multiple myeloma, the second one with newly diagnosed MM) additionally required a second apheresis to collect the target amount of CD34+ cells." (PMID 36672379, 2023). "A retrospective trial in patients with multiple myeloma (MM) showed that patients who received 12 mg of pegfilgrastim were capable of mobilizing a sufficient number of CD34+ cells compared with patients who received G-CSF." (PMID 33014813, 2020). "More importantly, the expression of transcription factors, such as GATA1 and KLF1, which govern erythrocyte differentiation, was significantly downregulated in CD34+ HSPCs from myeloma patients." (PMID 33239656, 2020). "Real-time PCR and Western blotting further indicated the recovery of GATA1 expression at both the mRNA and protein levels after blocking the CCL3/CCR1/phos-p38 signalling pathway in CD34+ cells from myeloma patients." (PMID 33239656, 2020). "Flow cytometry analysis revealed that the population of CD45+CD34+ HSPCs was significantly decreased in bone marrow biopsy samples of myeloma patients compared to the healthy controls (0.43% ± 0.04% vs. 1.84% ± 0.17%, p < 0.0001)." (PMID 33239656, 2020). "A total of 1243 differentially expressed genes (DEGs) were identified in CD34+ cells between myeloma patients (n = 8) and healthy donors (n = 3), 852 of which were upregulated and 391 of which were downregulated (FC > 2.0, p < 0.01)." (PMID 33239656, 2020). "We compared these results with the engraftment capacity of human CD34+ cells obtained from patients with multiple myeloma (MM)." (PMID 32781703, 2020). "The number of CD45+CD34+ HSPCs was negatively correlated with the number of CD38+CD138+ myeloma cells in the bone marrow of MM patients (r = − 0.6112, p < 0.0001)." (PMID 33239656, 2020). "The data indicated that colony formation, especially BFU-E colony formation, was significantly defective in myeloma CD34+ HSPCs compared to normal control CD34+ HSPCs (31.00 ± 3.98 vs. 44.40 ± 3.14, p < 0.01)." (PMID 33239656, 2020).
multiple myeloma (continued). "In particular, the expression of the master regulators of erythropoiesis, including GATA1 and KLF1, was obviously decreased in myeloma CD34+ cells (FC < − 2.0, p < 0.01)." (PMID 33239656, 2020). "Compared to the CD34+ cells from myeloma bone marrow, the expression of GATA1 in normal CD34+ slightly suppressed by the CCL3 treatment which also caused by pho-p38." (PMID 33239656, 2020). "Immunofluorescence staining indicated that CCL3 effectively activates p38 signalling with high levels of phosphorylated p38 in CD34+ cells derived from myeloma patients." (PMID 33239656, 2020). "The monoclonal antibody daratumumab, approved for treating myeloma, targets CD38, a protein on myeloma and also on CD34+ hematopoietic progenitor cells." (PMID 30356940, 2018). "Daudi cells have over 250,000 molecules of CD38 per cell on their surface while KG-1 cells have 85,000 per cell and CD34+ mobilized cells from myeloma patients have less than 10,000 per cell." (PMID 30356940, 2018). "Daratumumab then does not significantly impact the viability or colony-forming capacity of CD34+ progenitor cells from myeloma patients in vitro." (PMID 30356940, 2018). "Recently, in patients with non-Hodgkin lymphoma (NHL) or multiple myeloma (MM) with a poor yield of CD34+ cells, the new drug plerixafor (Mozobil®) can be administered before apheresis to increase the number of circulating CD34+ cells." (PMID 24722996, 2015). "Plerixafor in combination with granulocyte-colony stimulating factor (G-CSF) has been approved as mobiliser of haematopoietic CD34+ cells from the bone marrow to the circulation for patients with non-Hodgkin's lymphoma and multiple myeloma." (PMID 25669980, 2015). "Next, peripheral blood-mobilized CD34+ cells isolated from two patients with relapsed multiple myeloma were cultured as described for 8 days and then cytokine-starved and stimulated with either eltrombopag or rhTPO." (PMID 25886818, 2015). "Eltrombopag stimulated megakaryopoiesis in human CD34+ cells from normal individuals and from patients with relapsed multiple myeloma via activation of Akt signaling pathways." (PMID 25886818, 2015). "We show for the first time that eltrombopag is capable of stimulating megakaryopoiesis in CD34+ cells isolated from patients with relapsed multiple myeloma and did so to a degree equivalent to that of rhTPO." (PMID 25886818, 2015). "Cell-surface markers of established cell lines exhibit positive expression of CD138, CD45, and CD34 as shown in multiple myeloma cells from a patient at diagnosis." (PMID 25343143, 2014). "In the present study, RENIN and ANGTS mRNA expressions were significantly higher in CD34+ hematopoietic stem cells of healthy allogeneic donors in comparison to myeloma-related progenitor cells." (PMID 25035670, 2014). "The aim of this study is to examine critical RAS elements in normal CD34+ hematopoietic stem cells and multiple myeloma (MM)-related progenitor cells." (PMID 25035670, 2014). "It was recently seen that 2–4 × 106 CD34+ cells/kg body weight were recently defined as minimum dose for transplantation in patients with multiple myeloma (MM)." (PMID 25165572, 2014). "We thus conclude that the favourable effect of high numbers of circulating CD34+ cells is independent from the number of infused CD34+ cells at autologous transplantation in myeloma patients." (PMID 21878938, 2011). "The reason for the better clinical course of myeloma patients with large numbers of circulating CD34+ cells at the day of stem cell collection remains to be elucidated." (PMID 21878938, 2011). "In this retrospective study, we investigated the level of circulating CD34+ cells at the day of peripheral stem cell collection as a prognostic marker in myeloma patients." (PMID 21878938, 2011). "We determined circulating CD34+ cells at the day of peripheral stem cell collection in 158 consecutive myeloma patients between January 2001 and August 2010." (PMID 21878938, 2011).